RB1 (RB transcriptional corepressor 1)
Diseases named in the same sentence as RB1 in open-access papers (continued):
Sharing a sentence is not in itself a finding about the gene and the disease.
plasmacytoma (1 paper, 2022). Plasmacytoma is a localized mass of neoplastic monoclonal plasma cells that represents approximately 5% of all plasma cell neoplasms.
pleural mesothelioma (1 paper, 2022). A neoplasm that arises from the mesothelial cells of the pleura.
poorly differentiated thyroid carcinoma (1 paper, 2025).
pterygium (1 paper, 2020). A wedge-shaped fibrovascular lesion arising from the bulbar conjunctiva and extending to the cornea. "There are 6 genes that are highly expressed in pterygium, MYC, CDH2, CCNB1, RELN, RB1, and ERBB4." (PMID 33299863, 2020). "We presume that the LINC00472 network might function in pterygium via the FOXM1 PATHWAY, especially through the regulation of CCNB1, MYC, ERBB4, RELN, RB1, and CDH2 in the ceRNA network." (PMID 33299863, 2020).
retinal (1 paper, 2022). "In this study, heterozygous RB1 mutation displayed pathological characteristics in retinogenesis, such as focal neural retinal (NR) dysplasia." (PMID 36714839, 2022).
retinal degeneration (1 paper, 2017). Degeneration of the retina. "In the current study, PNS treatment was first shown to be protective against bright light-induced retinal degeneration in mice, which was recapitulated by the treatment of natural combination of saponin components Rb1 and Rd." (PMID 28729651, 2017). "Given significant implication of oxidative stress in retinal degeneration, attenuation of retinal oxidative stress could in part account for the retinal protective effects of natural combination of Rb1 and Rd." (PMID 28729651, 2017).
schwannoma (1 paper, 2024). A benign, usually encapsulated slow growing tumor composed of Schwann cells. "In fact, the differential diagnosis between schwannoma and our case is extremely difficult in aspect of morphologic features; however, the positive findings of ER, desmin, and CD34, with heterogenous loss of Rb1, in IHC contributed to the accurate diagnosis." (PMID 39493459, 2024).
skin telangiectasias (1 paper, 2023). "We next assessed the p-RB1 level in skin telangiectasias of two HHT2 patients." (PMID 37745444, 2023). "Phosphorylated retinoblastoma (p-RB1)—a marker of G1/S transition through the restriction point—significantly accumulated in ECs of HHT mouse retinal AVMs and HHT patient skin telangiectasias." (PMID 37745444, 2023). "We further found that p-RB1 increased in ECs of BMP9/10ib mouse AVMs and HHT patient skin telangiectasias." (PMID 37745444, 2023).
spindle cell sarcoma (1 paper, 2013). A malignant mesenchymal neoplasm composed of spindle-shaped cells. "A high frequency of retinoblastoma (Rb1) gene mutation has been reported in a subset of human eRMS, and we previously reported that Rb1 nullizygosity in combination with other mutations may lead to loss of differentiation in eRMS and spindle cell sarcomas." (PMID 24274149, 2013).
supraglottic cancers (1 paper, 2020). "Cell cycle proteins including CHEK2, CCNE1, and phosphorylated RB1 were expressed at higher levels in the supraglottic cancers, which may indicate a disruption in the G1/S transition." (PMID 33396315, 2020). "Of note, cancer related proteins RB1, CHEK2, CCNE1, S6 and PIK3CA were higher in the supraglottic cancers, whereas PDL1 was higher in the glottic cancers." (PMID 33396315, 2020).
tonsil (1 paper, 2023). "In HPV-associated and -unrelated TCGA tonsil cancer data, the tendency for CDKN2A (0% vs. 16.7%, respectively), FGFR3 (6.3% vs. 0%, respectively), and RB1 (9.4% vs. 7.9%, respectively) expression was comparable to that observed in our cohort." (PMID 36979829, 2023).
urothelial neoplasm (1 paper, 2019). A neoplasm involving a urothelium. "The molecular distinction between low- and high-grade non-invasive urothelial neoplasms, as well as flat CIS, shows a loss of function of a suppressor gene mutation, retinoblastoma 1 (RB1)." (PMID 30956908, 2019).
vitiligo (1 paper, 2014). Generalized well circumscribed patches of leukoderma that are generally distributed over symmetric body locations and is due to autoimmune destruction of melanocytes. "In general, these results suggest that Rb1 and Rg1 could be useful for photoprotection and treating vitiligo." (PMID 24799945, 2014). "Additionally, Rb1 or Rg1 could be useful for skin photoprotection and may represent an alternative treatment for vitiligo." (PMID 24799945, 2014).
Williams syndrome (1 paper, 2009). "Similarly, the frequency of SD cells in the samples from the Williams syndrome patients ranged from 12% to 31% for the SNRPN locus and from 29% to 51% for the RB1 locus with a mean of 23.4 ± 6.5% and 36.2 ± 6.7%, respectively." (PMID 19284877, 2009). "However, in the cell samples from the DGS/VCFS and the Williams syndrome patients, the frequency of SD cells for the imprinted SNRPN locus were significantly lower than the corresponding values for RB1 (P < 0.001 for the DGS/VCFS patients and P < 0.0002 for those with Williams syndrome)." (PMID 19284877, 2009).
tumor (2,384 papers, 1989 to 2026). "E7 proteins from high- and low-risk HPV genotypes bind directly to at least two tumor suppressors, RB1 and PTPN14, and inactivate both." (PMID 41890011, 2026). "Germline RB1 mutation also predisposes to intracranial midline neoplasms of the pineal or/and suprasellar region (trilateral RB)." (PMID 39729290, 2025). "Mutations in RB1, high levels of tumor mutation burden, natural killer cells, and interferons, and low levels of cancer-associated fibroblasts, correlated with prolonged PFS." (PMID 39962074, 2025). "CN estimation of epithelial cells revealed that two out of eight tumor samples contained a broad deletion in chromosome 13, which led to the loss of RB1 and its neighboring genes." (PMID 40904703, 2025). "The pathogenesis of retinocytoma is predominantly linked to mutations in the RB1 gene, a tumor suppressor gene located on chromosome 13q14." (PMID 40001157, 2025). "A key finding of this study is the potential direct transcriptional regulation of STMN1 by E2F1 and the correlation between STMN1 expression and RB1 loss, a critical tumor suppressor in PCa." (PMID 39776361, 2025). "Actually, we detected deletion of RB1 in one OS tumor as a specific acquired tumor somatic mutation corresponding to an 8% frequency of RB alterations in our small cohort of OS patients." (PMID 41514647, 2025). "In conditional knockout models, Rb1 loss is sufficient to drive metastasis and lineage plasticity following tumor formation driven by Pten loss." (PMID 40840524, 2025). "Palbociclib, a selective inhibitor of the cyclin-dependent kinases CDK4 and CDK6, was found to enrich tumor organoids with RB1 mutations." (PMID 40507353, 2025). "RB-iPSC-ROs have been generated from patients and carriers of RB1 germline mutations to assess the influence of patient context on tumor formation." (PMID 39422807, 2025). "On the other hand, since RB1 cannot be considered as a therapeutic target, genes involved in RB1‐deficiency‐related aberrant signals and pathways were considered as actionable targets, such as transcriptional targets and tumor microenvironment." (PMID 40904703, 2025). "The presence of RB1 mutations impairs the normal regulatory function of pRB, resulting in deregulated cell cycle progression and potential tumor formation." (PMID 40001157, 2025). "The FGF/FGFR1/NOTCH1 within RB1 variant group has a dramatically inflamed microenvironment, showing higher inner‐tumor CD8+ T cell infiltration." (PMID 40001320, 2025). "The pathogenesis of RB is caused by the mutations of the RB1 gene, which is a tumor suppressor gene that leads to the loss of function of RB proteins and affects the cell cycle, eventually causing abnormal cell proliferation." (PMID 40344913, 2025).
tumor (continued). "The RB1-encoded retinoblastoma protein (RB) suppresses tumor growth by binding E2F transcription factors to silence proliferation genes, regulating cell cycle checkpoints, apoptosis, and differentiation." (PMID 41353695, 2025). "The loss of tumor suppressors such as RB1 and PTEN promotes cancer development; however, their role in neurodegeneration is more complex, involving a delicate balance in neuronal health and function." (PMID 41241298, 2025). "Consistent with the primary tumour, the mutation of the RB1 gene (chr13:49033890; c.2039T>C; p.Ile680Thr; coverage: 1985; allele frequency: 6.30%), was detected and classified as pathogenic." (PMID 40729029, 2025). "The retinoblastoma gene RB1 was the first tumor suppressor identified, and it is mutated in many types of cancer." (PMID 41336845, 2025). "Subsequent analyses have demonstrated the presence of somatic mutations in the RB1 gene in AH samples, consistent with findings from enucleated tumor tissue." (PMID 40332023, 2025). "Inactivation of RB1 was recognized in early studies to be a recurrent hallmark of tumor development and progression across many cancer types." (PMID 40138429, 2025). "Remarkedly, the FGF/FGFR1/NOTCH1 within RB1 variant group has a dramatically higher inner‐tumor CD8+ T cell infiltration, following more CD8+PD‐1‐LAG3‐ non‐exhausted T cells and CD8+PD‐1+LAG3‐ exhausted T cells." (PMID 40001320, 2025). "This tumor typically develops due to the loss of function of the RB1 gene, caused by single-nucleotide variants (SNVs), copy number variants (CNVs), loss of heterozygosity (LOH), or hypermethylation of the promoter." (PMID 40332023, 2025). "Similar to the LuCaP145.1 model, our results showed that the RB1-loss CRPC tumor is only sensitive to BI-1870." (PMID 40519166, 2025). "While biallelic RB1 loss initiates tumor formation, additional mutations (M3 to Mn) are usually required for tumor progression." (PMID 41002743, 2025). "Mechanisms of resistance, such as cyclin E overexpression, RB1 mutations, and bypass signaling pathways, highlight the complexity of tumor biology and the need for alternative therapeutic strategies." (PMID 39935426, 2025). "The retinoblastoma susceptibility gene (RB1) is a tumor suppressor gene that encodes the pRB protein, which prevents cell cycle progression from the G1 to S phase by binding and inhibiting the transcription factor E2F." (PMID 40867318, 2025). "RB1 is a tumor suppressor gene encoding the retinoblastoma protein critical for cell cycle regulation." (PMID 41009976, 2025). "Despite the apparent paradox of one tumor suppressor degrading another, the prior data describing the synthetic lethality of Vhl and Rb1 loss, and pRb’s role in modulating hypoxic cell death, led us to validate pRb as our top hit." (PMID 40240354, 2025). "The RB1 gene serves as the architect, encoding the retinoblastoma protein (pRB), a crucial tumour suppressor that governs the orderly progression of the cell cycle; thus, this pathway is regarded as the master regulator in RB pathogenesis." (PMID 38975183, 2024). "Ferroptosis induction, particularly through the RB/E2F/ACSL4 axis, emerges as a promising strategy for combating tumor growth driven by RB1 loss, offering potential clinical benefits in various cancer types." (PMID 38672640, 2024).
tumor (continued). "Analysis of AH from 10 patients who had undergone an eye enucleation identified all RB1 pathogenic variants characterised by clinical testing of the paired tumour DNA samples." (PMID 38672657, 2024). "The occurrence of SMNs in RB patients is also closely linked to germline variants in the RB1 tumor-suppressor gene." (PMID 39596402, 2024). "Previous studies have found mutations in the tumor suppressor gene RB1 to be associated with poor overall survival across multiple tumor types and within mCRPC15,37–40." (PMID 38396008, 2024). "The retinoblastoma gene (RB1), located in 13q14, encodes the retinoblastoma protein (pRB), a tumor suppressor that regulates cell cycle progression." (PMID 39664374, 2024). "Another probe, cg24342013, is located in the RB1 gene, which encodes another rather well-known tumour suppressor." (PMID 39595122, 2024). "Recently, several findings highlighted multiple methods as a promising strategy for combating tumor growth driven by RB1 loss, offering potential clinical benefits in various cancer types." (PMID 38672640, 2024). "Dysregulated E2F1 activity, driven by genetic and molecular alterations such as mutations in the RB1 gene, plays a pivotal role in disease development by promoting uncontrolled cell proliferation and tumor formation." (PMID 39000021, 2024). "In more than 95% of the cases, the tumor initially develops through biallelic loss of the tumor suppressor gene RB1 and further progresses after additional genetic/epigenetic changes (for review:)." (PMID 38674157, 2024). "This profile is consistent with an origin of the tumour in the cPR lineage, which is similar to the cell-of-origin for the RB1-deficient cancers." (PMID 37606819, 2024). "Five hits were found to regulate autophagy in NKX3-1-loss and RB1-loss tumors with three of these five hits overlapping between the two tumor subtypes." (PMID 38751776, 2024). "RB1 encodes tumour‐suppressing pRB proteins, the inactivation of which is often found in Neuroendocrine prostate cancer (NEPC), an aggressive subtype of the disease." (PMID 39410867, 2024). "On the other hand, even if some family members are heterozygous carriers of an oncogenic RB1 allele, hereditary RB has incomplete penetrance, resulting in some family members being tumour-free." (PMID 38975183, 2024). "A key finding of this study is the correlation between STMN1 expression and the loss of RB1, a critical tumor suppressor that regulates the cell cycle by binding to E2Fs and blocking their transcriptional activation." (PMID 39711570, 2024). "The protein product of the CDKN2A gene, p16, plays a critical role in cell cycle regulation via its interaction with the retinoblastoma tumor suppressor encoded by the RB1 gene." (PMID 39684714, 2024). "The increased level of E2f renders the cells to adopt a similar mechanistic phenotype to a RB1-deficient tumour." (PMID 37606819, 2024). "Patients with MM frequently exhibit RB1 mutations or deletions, leading to tumor cell independence from RB1 and promoting uncontrolled proliferation and dissemination." (PMID 39664374, 2024).